DKK1 (dickkopf Wnt signaling pathway inhibitor 1)
Diseases named in the same sentence as DKK1 in open-access papers (continued):
Sharing a sentence is not in itself a finding about the gene and the disease.
angina (4 papers, 2022 to 2025). "Plasma DKK-1 levels are associated with CKD in patients with angina." (PMID 40422877, 2025). "Our main finding in the present study is that plasma DKK-1 levels are inversely correlated with the eGFR in patients who have undergone coronary angiography for angina." (PMID 40422877, 2025). "Recently, we reported that plasma DKK-1 levels are predictive of major adverse cardiac events (MACEs) in patients with angina." (PMID 40422877, 2025). "A strength of the present study is that plasma DKK-1 levels have a synergistic effect with obstructive CAD on the prediction of long-term MACEs in patients who have experienced angina." (PMID 36291617, 2022). "However, higher plasma DKK-1 levels and obstructive CAD had a synergistic effect on predictions of a higher risk of MACEs in patients with angina during a median follow-up of 4.8 years." (PMID 36291617, 2022). "First, we did not directly assess the underlying mechanism involved in DKK-1 and MACEs in patients with angina." (PMID 36291617, 2022). "Notably, the coagulating process can induce the secretion of DKK-1, and serum DKK-1 levels have been reported to be higher in patients with angina than in controls." (PMID 36291617, 2022). "In conclusion, we observed a synergistic effect between high plasma DKK-1 and obstructive CAD on the prediction of MACEs in patients with angina." (PMID 36291617, 2022). "Plasma DKK-1 levels in patients with angina and significant coronary obstruction were not significantly different from those in patients with angina but no significant coronary obstruction." (PMID 36291617, 2022).
bladder cancer (4 papers, 2019 to 2024). "Moreover, the high-level expression of Dkk1 in preoperative advanced bladder cancer patients is closely associated with tumor stage, poor patient survival and distant metastasis." (PMID 36430344, 2022). "DKK-1, SDF-1, TGF-β, and RANTES have been found to increase the risk of developing bladder cancer in lots of researches." (PMID 31809208, 2019).
bone cancer (4 papers, 2018 to 2024). A primary or metastatic malignant neoplasm affecting the bone or articular cartilage. "Once bone tumors are established, Wnt/β-catenin signaling is involved in the suppression of osteoblast function largely through DKK1." (PMID 34685470, 2021). "The effects of Dkk-1 and SP600125 on cell proliferation, in vivo tumor growth, and bone tumor phenotype were investigated." (PMID 34437475, 2021).
cerebrovascular disease (4 papers, 2014 to 2020). "Activation of the Wnt pathway is known to support neuronal survival, and induction of the Wnt inhibitor, Dkk-1, contributes to neuronal death in experimental animal models of cerebrovascular disorders, AD, temporal lobe epilepsy, and stress-related disorders." (PMID 30258353, 2018). "In a study performed by Seifert-Held and co-workers, plasma levels of DKK1 were also significantly higher in patients with acute ischemic stroke, compared to patients with stable cerebrovascular disease, and healthy controls." (PMID 30496210, 2018). "T2DM patients with abnormal IMT (756±433 pg/ml vs 563±322 pg/ml; P = 0,042) and cerebrovascular disease (854±480 pg/ml vs 625±363; P = 0,045) had higher DKK1 concentrations." (PMID 25369286, 2014). "Interestingly, Dkk1 plasma levels were higher in patients with stable cerebrovascular disease when compared to healthy individuals." (PMID 33071819, 2020). "Patients with cerebrovascular disease have higher serum DKK1 levels compared with control subjects, and serum DKK1 correlated with coronary artery calcification and atherosclerotic plaques evaluated by coronary computed tomography and coronary artery calcium scoring." (PMID 25369286, 2014). "Furthermore, the levels of Dkk1 in the plasma of patients with acute ischemic stroke have been reported to significantly increase in comparison to healthy individuals, as well as patients with stable cerebrovascular disease." (PMID 33071819, 2020).
coronary artery disease (4 papers, 2014 to 2025). "Previous studies have documented elevated DKK-1 levels in patients with arteriosclerosis, coronary artery disease (CAD), or carotid plaques." (PMID 40299461, 2025). "In a previous study, DKK1 concentration was inversely co-related to aortic calcification and coronary artery disease." (PMID 37728820, 2023). "In a previous study from Register and colleagues, DKK1 concentrations were inversely related to coronary artery disease and aortic calcification." (PMID 25369286, 2014). "Interestingly, plasma levels of DKK1 seem to increase with increasingly unstable coronary disease." (PMID 30496210, 2018).
dementia (4 papers, 2019 to 2025). Loss of intellectual abilities interfering with an individual's social and occupational functions. "Dickkopf1 (Dkk1) is the most well‐characterized inhibitor of Wnt signaling, and its production increases in aging and dementia models." (PMID 40637118, 2025). "DKK1 and sclerostin are bone-related factors showing promise as potential biomarkers for dementia prediction." (PMID 40700291, 2025). "Moreover, given that DKK1 is overexpressed in Alzheimer’s brain while the activation of Wnt signaling rescues neurodegeneration, the inhibition of Wnt signaling by DKK1 might be a critical factor in neuronal dysfunction associated with dementia." (PMID 36291101, 2022). "Current evidence implicates DKK1 in the amyloid-induced toxicity that underpins AD progression and highlights the emergence of sclerostin as a bone-related biomarker with potential for early dementia detection." (PMID 40700291, 2025). "To date, there is only one other study which examined serological Dkk-1 in a cohort of older adults with subjective cognitive concerns but in the absence of clinically diagnosed dementia." (PMID 31680933, 2019).
diabetic kidney disease (4 papers, 2022 to 2025). Progressive kidney disorder caused by vascular damage to the glomerular capillaries, in patients with diabetes mellitus. "Silencing DKK1 prevented kidney function impairment and microstructural changes in diabetic nephropathy." (PMID 40922300, 2025). "DKK1 may accelerate the progression of diabetic nephropathy, and DKK1 inhibition may be considered a therapeutic approach for this disease." (PMID 40922300, 2025).
end-stage renal disease (4 papers, 2019 to 2025). "Due to a high variability in the speed of CKD progression to end-stage renal disease (ESRD) and the critical involvement of Wnt/β-catenin signaling in CKD, we investigated the role of the Wnt antagonist Dickkopf-1 (DKK1) in CKD progression." (PMID 37108841, 2023).
fibrosis (4 papers, 2020 to 2023). the formation of excess fibrous connective tissue in an organ or tissue in a reparative or reactive process. "He and co-workers also found that the Wnt antagonist DKK1 reduces β-catenin deposition in UUO mouse kidneys as well as fibrosis occurrence." (PMID 32484208, 2020). "Moreover, inhibition of DKK1 in vivo can alleviate PM2.5-induced pulmonary inflammation and fibrosis." (PMID 33012781, 2020).
glaucoma (4 papers, 2017 to 2022). Increased pressure in the eyeball due to obstruction of the outflow of aqueous humor. "Results showed that 8 genes were significantly changed, 6 of which were down‐regulated in glaucoma, such as WNT7B and DKK1." (PMID 31680442, 2020). "Examples of these include genetic models of glaucoma (MyocY437H mice), OHT induced by transduction of the TM with glaucoma-related genes (e.g., MYOC, TGFβ2, GREM1, CTGF, DKK1, SFRP1, CD44, Cre and inducible transgene models, genome editing), as well as glucocorticoid-induced OHT models." (PMID 35129590, 2022). "In contrast to DKK1, the potential role of CDH6 in glaucoma pathogeneses is currently unclear." (PMID 28068412, 2017).
lupus nephritis (4 papers, 2014 to 2025). Glomerulonephritis in the context of systemic lupus erythematosus. "In this report, an increased canonical Wnt/β-catenin signaling activity was determined in kidneys of (NZB × NZW) F1 mice during progression of lupus nephritis, which was paralleled by an increase in renal and serum levels of DKK-1." (PMID 28373995, 2017). "The canonical WNT/β-catenin signaling pathway was activated in lupus nephritis patients, accompanied by an increase in plasma levels of Dkk-1." (PMID 24465439, 2014). "Considering the relationship between Dkk-1, C3 and anti-dsDNA antibody, our data suggested that Dkk-1 might play a protective role in lupus nephritis." (PMID 24465439, 2014).
malignant glioma (4 papers, 2010 to 2025). A grade III or grade IV glioma arising from the central nervous system. "We demonstrate that DKK-1 is expressed by malignant glioma cells but not by other tumor cell lines investigated using RT-PCR and ELISA." (PMID 21029453, 2010).
metastasis (4 papers, 2014 to 2023). The spread or migration of cancer cells from one part of the body (where they first appeared) to another. "DKK1 levels inversely correlated with tumor class, TNM stage, distant metastasis and lymph node metastasis of GC." (PMID 26799283, 2016).
metastatic cancer (4 papers, 2008 to 2024). A carcinoma which has spread from the original site of growth to another anatomic site. "DKK1 inhibitors have demonstrated efficacy in inhibiting metastasis, suggesting a potential therapeutic strategy for metastatic cancer." (PMID 39505867, 2024). "We demonstrated ex vivo that osteoclastogenesis is an active mechanism in tumour nesting of bone forming metastatic cancer and that serum DKK-1 levels are increased in CaP patients, suggesting to deeply investigate its role as tumour marker." (PMID 18978943, 2008). "Taken together, these observations suggested that RBM47-dependent suppression of tumor progression was partially mediated by its ability to increase the production of the Wnt antagonist DKK1, a secreted protein that can inhibit tumor phenotypes in metastatic cancer cells." (PMID 24898756, 2014).
myopia (4 papers, 2014 to 2024). "We measured circulating DKK-1 levels in the patients with myopia and their association with the risk of myopia." (PMID 34259818, 2021). "Inhibiting the canonical Wnt signaling pathway through DKK1 leads to reduced axial length elongation, thereby attenuating myopia progression." (PMID 39625993, 2024). "Investigations have shown that reduced serum levels of niclosamide (DKK-1), a Wnt pathway inhibitor, correlate with myopia, and that activation of the canonical Wnt pathway is a feature of myopia progression in mice." (PMID 39625993, 2024). "–14 Furthermore, inhibition of the canonical Wnt signaling pathway by antagonist Dickkopf-1 (DKK-1) reduced the myopic shift in refractive error, which suggested that canonical Wnt signaling pathway were vital for myopia development." (PMID 34259818, 2021). "Nonetheless, a report from Zhang noted raised concentrations of DKK-1 in vitreous fluid of patients with pathological myopia, which is in disagreement with our findings in plasma." (PMID 34259818, 2021). "Meanwhile, larger prospective trials should be performed to further validate whether the patients with myopia with low levels of DKK-1 prior to any therapy had a significantly more myopic development than those patients with high DKK-1 levels." (PMID 34259818, 2021). "Plasma level of Wnt inhibitor DKK-1 was markedly decreased in patients with myopia." (PMID 34259818, 2021). "In our study, we measured the plasma levels of DKK-1 in patients with myopia and healthy controls." (PMID 34259818, 2021). "The amounts of Wnt2b, Fzd5 and β-catenin mRNA and protein were significantly greater in form-deprived myopia eyes than in control eyes.DKK-1 (antagonist) reduced the myopic shift in refractive error and increase in axial elongation, whereas Norrin had the opposite effect in FDM eyes." (PMID 24755605, 2014). "Thus, the abnormality of the BRB that exists in myopia could affect the vitreous level of DKK-1, which may need to be further investigated after normalization to total vitreous protein concentrations." (PMID 34259818, 2021). "Levels of DKK1 and MMP-2 were significantly higher in the pathologic myopia group than in the low-to-moderate myopia and control groups." (PMID 39597899, 2024). "The levels of Dickkopf 1 (DKK1) and matrix metalloproteinase 2 (MMP-2) in the vitreous humor of patients with myopia." (PMID 39597899, 2024).
oral cancer (4 papers, 2014 to 2021). "However, it was found that the expression of DKK1 correlated significantly with a low risk of regional lymph node metastasis and that its knockdown increased the cellular migration and invasiveness in oral cancer cells." (PMID 25487617, 2015). "As a result, by western blot analysis, the protein expression level of β-catenin and the downstream targets such as DKK1 and Axin2 are highly upregulated in oral cancer SCC-55 cells compared to control cells." (PMID 34632073, 2021). "DKK1 knockdown increased cellular migration and invasiveness in oral cancer cells." (PMID 32286381, 2020).
osteogenesis imperfecta (4 papers, 2019 to 2025). Osteogenesis imperfecta (OI) comprises a heterogeneous group of genetic disorders characterized by increased bone fragility, low bone mass, and susceptibility to bone fractures with variable severity. "AGA-2115 (Angitia Biopharmaceuticals) is also a humanized bispecific antibody that targets sclerostin and DKK1 which is in Phase 1 clinical development for the treatment of osteogenesis imperfecta." (PMID 40394415, 2025). "Similarly, sera from children with osteogenesis imperfecta contains elevated DKK1 and RANKL and inhibits osteoblast differentiation in vitro." (PMID 31197079, 2019). "In addition, when DKK1 and RANKL levels were significantly and simultaneously increased, osteoblast differentiation and OPG expression were more inhibited in patients with osteogenesis imperfecta with higher DKK-1 levels, demonstrating that DKK-1 has a more detrimental effect on bone formation." (PMID 37106471, 2023).
psoriasis (4 papers, 2010 to 2023). An autoimmune condition characterized by red, well-delineated plaques with silvery scales that are usually on the extensor surfaces and scalp. "Compared with both healthy controls and psoriasis controls, patients with PsA had higher circulating concentrations of Dkk-1 and M-CSF." (PMID 20796300, 2010). "Compared with those with psoriasis and healthy controls, patients with PsA had higher circulating concentrations of Dkk-1 and M-CSF." (PMID 20796300, 2010). "A key finding of this study is the elevated serum Dkk-1 concentrations with patients with PsA, compared with those in patients with psoriasis and healthy control participants." (PMID 20796300, 2010). "Both subgroups had higher DKK1 serum concentrations than the psoriasis group." (PMID 37750896, 2023). "Patients with both erosive and nonerosive PsA had higher circulating concentrations of Dkk-1, compared with psoriasis controls." (PMID 20796300, 2010).
renal carcinoma (4 papers, 2012 to 2019). A carcinoma arising from the epithelium of the renal parenchyma or the renal pelvis. "Similarly, a significant decrease in DKK1 expression was observed in renal cancer tissues, and a tumor suppressor effect was demonstrated following the transfection of renal cancer cell lines with recombinant plasmids containing the DKK1 gene." (PMID 31568519, 2019). "Also, in osteolytic-type tumor metastases (most common in metastasis of breast, lung and renal cancer), the enhanced differentiation and resorption activity of OCs, is also accompanied by suppressed OB formation due to DKK-1 secretion from tumor cells." (PMID 22539950, 2012).
Sepsis (4 papers, 2017 to 2023). Sepsis is defined as life-threatening organ dysfunction caused by a dysregulated host response to infection. "The most common causes of death were sepsis (four for the DKK1-high group; three for the DKK1-low group) and cardiovascular diseases (one for the DKK1-high group; four for the DKK1-low group)." (PMID 37108841, 2023). "Our results thus far suggested that inhibition of Dkk1 activity may be exploited to restrain overshooting cytokine production, a hallmark of sepsis." (PMID 36539532, 2022). "DKK1 levels in the blood are elevated in a variety of disorders with infections, including viral infection, pneumonia and sepsis." (PMID 37942584, 2023). "In this study, LPS-induced pro-inflammatory cytokine expressions in HUVECs were significantly suppressed by DKK-1 or LGK974, suggesting that their anti-inflammatory effects may be useful for the treatment of vascular inflammation and sepsis." (PMID 28128299, 2017).
squamous cell carcinoma (4 papers, 2015 to 2024). A carcinoma arising from squamous epithelial cells. "In this work, our screening uncovered previously unidentified prognostic gene expression indicators, namely, MYO1E, FAM83 homologs, and DKK1 for adenocarcinoma, and FGA and TRIB1 for squamous cell carcinoma." (PMID 39513892, 2024).
systemic sclerosis (4 papers, 2016 to 2022). A chronic disorder, possibly autoimmune, marked by excessive production of collagen which results in hardening and thickening of body tissues. "However, in patients with systemic sclerosis Dkk-1 is strikingly absent from the skin." (PMID 32185280, 2017).
temporal lobe epilepsy (4 papers, 2012 to 2025). A localization-related (focal) form of epilepsy characterized by recurrent seizures that arise from foci within the temporal lobe, most commonly from its mesial aspect. "In vivo, Dkk1 inhibition is neuroprotective in a model of temporal lobe epilepsy induced by kainic acid injection and in different models of cerebral ischaemia." (PMID 23251385, 2012).
acute myeloid leukemia (3 papers, 2014 to 2019). Acute myeloid leukemia (AML) is a group of neoplasms arising from precursor cells committed to the myeloid cell-line differentiation. "Exosomes secreted from acute myeloid leukemia (AML) cells create a leukemic niche at the bone marrow (BM) to promote leukemic cell proliferation by inducing DKK1 and suppress normal hematopoiesis through exosome secretion." (PMID 32010626, 2019). "Interestingly, it has been suggested that exosomes derived from acute myeloid leukemia (AML) cells are able to induce expression of the Wnt-signaling inhibitor DKK1 in bone marrow stromal cells, thereby promoting osteoblast loss." (PMID 31083455, 2019).
autoimmune disease (3 papers, 2017 to 2025). A disorder resulting from loss of function or tissue destruction of an organ or multiple organs, arising from humoral or cellular immune responses of the individual to their own tissue constituents. "However, a negative correlation with the same anatomical region has been reported in other populations with autoimmune diseases without anti-TNF treatment; then, the use of biological treatments could influence the behavior of DKK-1." (PMID 40981186, 2025).
basal cell carcinoma (3 papers, 2017 to 2021). A carcinoma involving the basal cells. "KEGG enrichment analysis indicated upregulated DEGs were involved in Renin-angiotensin system (e.g., Agt, angiotensinogen) and Wnt signaling pathway (e.g., Dkk1), while downregulated DEGs participated in Basal cell carcinoma (e.g., Lef1)." (PMID 29121993, 2017). "As a result, 24 KEGG pathways were enriched for upregulated DEGs, including Renin-angiotensin system (e.g., Agt, angiotensinogen), Renin secretion (e.g., Agt), and Wnt signaling pathway (e.g., Dkk1), while 16 pathways were for downregulated DEGs, including basal cell carcinoma (e.g., Lef1)." (PMID 29121993, 2017).